DRD2 (dopamine receptor D2)
Diseases named in the same sentence as DRD2 in open-access papers (continued):
Sharing a sentence is not in itself a finding about the gene and the disease.
cancer (continued). "By providing the dual benefit of increasing therapeutic potency while reducing toxic side effect profiles, TDZ+ represents a promising lead compound for the future development of DRD-targeted therapies in AML and potentially a variety of cancers that also aberrantly express DRD2." (PMID 33665638, 2021). "DRD2 might trigger different polarization of macrophage in inflammation disease and in carcinoma, even in different cell types." (PMID 33859743, 2021). "Additionally, pharmacological antagonism of DRD2 or knockdown DRD2 expression by siRNA has been shown to have anti-cancer effects, including studies using SEC cells." (PMID 33194693, 2020). "ONC201 is a first-in-class small molecule selective DRD2 antagonist that is in Phase II clinical trials in select advanced cancers, including type 1 and 2 ECs, after completion of a promising first-in-man clinical trial in advanced solid tumors that included EC patients." (PMID 33194693, 2020). "In addition, another study showed TFP was able to reduce the angiogenesis and invasion of aggressive cancer cells via DRD2 to modulate the β-catenin pathway." (PMID 31572198, 2019). "We reasoned that if DRD2 is driving the self-renewal of cancer cells in vivo, dopamine may be present in human tumors." (PMID 31822725, 2019). "This has been implicated in previous study which showed that downregulation of DRD2 whether through transient knockdown of the receptor or pharmacological antagonism can have cytotoxic effects towards cancer cells." (PMID 30405882, 2018). "We observed an inverse correlation between CDH13 methylation (p = 0.045; r = -0.21) and serum vitamin D level whereas TIMP3 methylation (p = 0.021; r = -0.24) and DRD2 methylation (p = 0.056; r = -0.201) showed inverse correlation with supplementary vitamin D in the cancer cases." (PMID 30204798, 2018). "Since c-Myc, KLF5, and DRD2 have been suggested to increase cancer stem cell-like populations in various tumors, reducing these proteins in response to BPD and TFP suggests a novel FOXO3-dependent mechanism underlying BPD- and TFP-induced apoptosis in TNBC cells." (PMID 27283899, 2016). "The different DRD2 expression and behavior of E-MSCs might be due to selection and/or epigenetic modulation of the extrauterine microenvironment found in ectopic sites, as reported for cancer lesions." (PMID 35163699, 2022). "To assess DRD2 and CLPP expression in human cancers, we verified the different expression for both genes across TCGA tumors by the TIMER database." (PMID 40699850, 2025). "When applied to ONC201, a molecule under clinical development designated for the treatment of cancer, BANDIT identified and validated DRD2 as its target." (PMID 41183148, 2025). "Dopamine receptor D2 (DRD2) was down-regulated with low ALKBH5, and studies have shown DRD2 to be up or down-regulated in different cancer types." (PMID 39127986, 2024). "ONC201 was originally developed as a brain-penetrant dopamine receptor D2 (DRD2) antagonist and is tolerable for cancer therapy." (PMID 38299592, 2024). "Here, we performed analysis of DRD2 and CLPP mRNA expression levels obtained from publicly available pediatric cancer transcriptomic data sets, established by St." (PMID 37589388, 2024). "Therefore, DRD2 antagonists might be promising repurposed drugs for cancer treatment." (PMID 35461314, 2022). "DRD2 has emerging as a novel therapeutic target in GBM and other cancers based on a series of studies that have demonstrated its selective overexpression in malignant tissues and the anticancer effects of its antagonism." (PMID 34503167, 2021). "Targeting DRD2 with ONC201 has shown promising results in vitro and in vivo preclinical models in some types of cancers." (PMID 33557912, 2021). "Cancer stem cells have been shown to express relatively high levels of DRD2 compared to the bulk population and ONC201 effectively depletes cancer stem cells in numerous malignancies." (PMID 29108308, 2017).
cancer (continued). "Because it has been suggested that several cancer-promoting genes, such as Akt, c-Myc, KLF5, and DRD2 are involved in cell survival or proliferation in BCa cells, we sought to compare the status of these genes in human TNBC tumors versus non-TNBC tumors." (PMID 27283899, 2016). "Unexpectedly, we uncover that both TFP and BPD display suppression of the expression of the dopamine receptor D2 (DRD2), which has been suggested as a key receptor for selective-targeting cancer stem cells (CSC), in a FOXO3-dependent manner." (PMID 27283899, 2016). "Constitutive activation of dopamine receptors DRD1, DRD2, DRD5 has been reported in relation to development and neurological disease, but the impact of the functional change on cancer progression and metastasis remains unclear." (PMID 39679842, 2025). "The most investigated genes were those implicated in neuroendocrine stress responses; dopamine, norepinephrine, and serotonin signalling; apoptosis; insulin secretion; neuroplasticity; reproduction; foetal growth; and cancer (e.g. MAOA, BRSK2, ADCYAP1, BDNF, DRD2, IGF2, H19)." (PMID 41070359, 2025). "Recently, DRD2 was reported to be upregulated in various cancers and tied to the stemness of solid and nonsolid tumors." (PMID 35461314, 2022). "Several studies suggested potential cross-talk between DRD2 with nAChRs within the brain, but no conclusive evidence of their interaction in cancer has been observed till now." (PMID 36072788, 2022). "The results from the present study indicate that the efficacy of mechanical loading and FP in cancer cells may depend on the expression levels of DRD1 and DRD2." (PMID 34031366, 2021). "Another DRD2 agonist, dopamine, also did not significantly increase cancer cell motility." (PMID 36428628, 2022). "Therefore, this peptide may not be useful as a potent drug with therapeutic efficacy in cancers expressing DRD2 receptors, for which DRD2 antagonism is important to produce antitumor effects." (PMID 36428628, 2022).
neurological diseases (26 papers, 2015 to 2025). "Mutations in the human DRD2 gene encoding the DA uptake receptor and release inhibitor D2 might be associated with some psychiatric and neurological diseases." (PMID 35629417, 2022). "The Dopamine receptor D2 (DRD2) gene has been investigated as a candidate gene in several psychiatric and neurological disorders involving dopaminergic systems." (PMID 40727586, 2025). "DRD2 and DRD3 belong to the D2-like receptors and are normally associated with neurological diseases." (PMID 32867127, 2020). "The mRNAs of Rgs9, Gpr88, Drd2, Sh3rf2, Tac1, Serpina 9, Rxrg, Drd1, Rasgrp2, Six3, Gpr6, Pdyn, Gng7, and Pde1b were all upregulated (p < 0.05); all of these have been reported to be more or less related to nervous system diseases." (PMID 33819195, 2021). "As the offspring became older (16 months of age), we found that some genes of benefit to nervous system disease were activated, such as Lhx8, GPR88, RGS9, CD4, DRD2, RXRG, and Syt6, following the increase in the number of cholinergic and GABAergic neurons." (PMID 33819195, 2021). "In the present study, we found that some genes of benefit to nervous system disease were activated (such as Lhx8, GPR88, RGS9, CD4, DRD2, RXRG, and Syt6), following the increase in the number of cholinergic and GABAergic neurons in the HSHF-diet offspring." (PMID 33819195, 2021). "When the offspring grew older (16 months), we found that some genes of benefit against nervous system disease were activated, such as Lhx8, GPR88, RGS9, CD4, DRD2, RXRG, and Syt6, and the expression of cholinergic and GABAergic neurons biomarker protein increased." (PMID 33819195, 2021).
movement disorder (17 papers, 2012 to 2025). Neurological conditions resulting in abnormal voluntary or involuntary movement, which may impact the speed, fluency, quality and ease of movement. "The dystonic epochs and coordination deficits observed in KCTD5 KO reflect hyperkinetic movement disorder pathology observed in patients with polymorphisms in signal transduction machinery, including DRD2, GNAL, GNAO1, and GNB1." (PMID 40233107, 2025). "Recently, mutations in DRD2 (WT), p.Ile212Phe (I212F), and p.Met345Arg (M345R) have been associated with hyperkinetic movement disorders and shown to alter heterotrimeric G-protein complex signaling and β-arrestin recruitment." (PMID 39857630, 2024). "Pathogenic mutations in many of these genes (such as DRD2, GNAL, GNAO1, ADCY5, and PDE10A) have been identified in patients with movement disorders (such as dystonia and dyskinesia)." (PMID 40233107, 2025). "In a population with chronic mental illness, various SNPs in 10 candidate genes (PPP1R1B, BDNF, DRD3, DRD2, HTR2A, HTR2C, COMT, MnSOD, CYP1A2, and RGS2) reached nominally significant (p≤0.05) associations with drug-induced movement disorder." (PMID 22615781, 2012). "High DRD2 expression could lead to the colon being underpowered and the generation of movement disorders." (PMID 37601055, 2023).
infection (12 papers, 2017 to 2024). The state of being infected such as from the introduction of a foreign agent such as serum, vaccine, antigenic substance or organism. "The dopamine receptor D2 antagonist alimemazine, one of the phenothiazines, was previously shown to effectively inhibit the infection of SARS-CoV-2 by interfering with the interaction between the SARS-CoV-2 S protein and neuropilin-1." (PMID 37632009, 2023). "An alternative explanation is that DRD2-5-HT2R heterodimers may act as a decoy receptor to limit host-cell infection." (PMID 36560603, 2022). "Expression levels of 5-HT2Rs and DRD2 stable cells were compared to previously published 5-HT2AR-YFP, 5-HT2BR-YFP, and 5-HT2CR-YFP stable cells that support an increase in JCPyV entry and infection compared to control HEK293A cells." (PMID 36560603, 2022). "DRD2 was selected because it is also a GPCR but is not required by JCPyV for entry or infection." (PMID 36560603, 2022).
brain disorder (8 papers, 2010 to 2022). A disease affecting the brain or part of the brain. "Determining the temporal and spatial expression pattern of Drd2 is a prerequisite for understanding its physiological function and pathophysiological roles in brain diseases." (PMID 30604007, 2019).
neurodegenerative disease (8 papers, 2010 to 2025). A disorder of the central nervous system characterized by gradual and progressive loss of neural tissue and neurologic function. "Dopamine D2 receptor (Drd2) has been regarded as a potential anti-inflammatory target in the therapy of neurodegenerative diseases." (PMID 30200997, 2018).
metabolic disorders (7 papers, 2015 to 2024). "Evidence has shown that DRD2 pathway regulates inflammation, and this effect cause metabolic disorders such as weight gain." (PMID 36188456, 2022). "Preliminary evidence indicates that SCZ is associated with reduced dopamine D2 receptor (DRD2) signaling, which significantly regulates the ER stress pathway, suggesting the importance of ER stress in SCZ and its related metabolic disorders." (PMID 36188456, 2022). "Hypothalamic ER stress may be activated by reduced DRD2 signaling that is part of the pathogenesis of SCZ and SCZ-related metabolic disorders, but additional studies are needed." (PMID 36188456, 2022). "Reduced DRD2 signaling in the hypothalamus is known to increase food intake, body weight, and regulate glucose metabolism, suggesting that the reduced DRD2 signaling may also be related to SCZ-related metabolic disorders such as increased BMI and abnormalities in glucose metabolism." (PMID 36188456, 2022).
central nervous system disorder (3 papers, 2018 to 2022). A disease involving the central nervous system. "Dopamine receptor D2 (D2R) has been shown to be involved in central nervous system diseases." (PMID 35889317, 2022).
endocrine disorders (1 paper, 2020). "The D2 dopamine receptor (DRD2) is one of the most well-established therapeutic targets for neuropsychiatric and endocrine disorders." (PMID 32103023, 2020).
DRD2 also shares sentences with these, for which no sentence is quoted: Parkinsonism (27 papers); metabolic syndrome (12); cocaine use disorder (7); hyperprolactinaemia (7); acromegaly (6); autism spectrum disorder (6); encephalitis (6); Autoimmunity (5); Delusion (5); gastroparesis (5); obsessive-compulsive disorder (5); amyotrophic lateral sclerosis (4); autoimmune disease (4); breast tumor (4); essential hypertension (4); Intellectual disability (4); non-small cell lung carcinoma (4); restless leg syndrome (4); sleep disorder (4); autoimmune encephalitis (3); cognitive disorder (3); drug dependence (3); Hallucinations (3); impulse control disorder (3); neurodevelopmental disorder (3); neuroleptic malignant syndrome (3); panic disorder (3); polycystic ovary syndrome (3); renal cell carcinoma (3); streptococcal infection (3).
A further 153 diseases each share a sentence with DRD2 in 2 papers or fewer.